EFCAB10 (EF-hand calcium binding domain 10)
Tractability: No criterion of Open Targets' tractability assessment is met for any kind of drug.
Gene: Protein-coding gene on chromosome 7 (105,565,120 to 105,600,875, reverse strand). Ensembl gene ENSG00000185055.
Gene Ontology:
Molecular function: calcium ion binding
Genetic constraint (gnomAD): Loss-of-function variants: 1 observed, 1.1 expected, observed/expected ratio (o/e) 0.91, 90% interval 0.25 to 1.88. That is too few expected variants to judge how well the gene tolerates losing a copy.
Homologues: Orthologues: chimpanzee EFCAB10 (99% identical), macaque EFCAB10 (94% identical), dog EFCAB10 (78% identical), rabbit EFCAB10 (76% identical), rat Efcab10 (75% identical), guinea pig EFCAB10 (74% identical), mouse Efcab10 (71% identical), pig EFCAB10 (71% identical), tropical clawed frog efcab10 (41% identical), zebrafish si:dkey-42p14.3 (37% identical). Paralogues in human: TEX55 (17% identical).
Diseases named in the same sentence as EFCAB10 in open-access papers:
EFCAB10 is named in the same sentence as 1 disease in open-access papers, as found by Europe PMC text mining. Sharing a sentence is not in itself a finding about the gene and the disease.
EFCAB10 shares sentences with these, for which no sentence is quoted: breast carcinoma (1 paper).